R3HCC1 (R3H domain and coiled-coil containing 1)
Synonyms: DKFZp564N123
Tractability: PROTAC: ubiquitination databases record sites on it; its protein half-life has been measured.
Gene: Protein-coding gene on chromosome 8 (23,270,120 to 23,296,279, forward strand). Ensembl gene ENSG00000104679.
Subcellular location (Human Protein Atlas): Cytosol; Nucleoplasm
Gene Ontology:
Molecular function: nucleic acid binding
Genetic constraint (gnomAD): Loss-of-function variants: 33 observed, 38.25 expected, observed/expected ratio (o/e) 0.86, 90% interval 0.65 to 1.15. The upper end of that interval is the gene's LOEUF score, 1.15, which puts it in group 5 of 6, group 1 being the genes least tolerant of losing a copy. Missense variants: 581 observed, 563.86 expected, observed/expected ratio (o/e) 1.03, 90% interval 0.96 to 1.1. Synonymous variants: 235 observed, 236.78 expected, observed/expected ratio (o/e) 0.99, 90% interval 0.89 to 1.11.
Homologues: Orthologues: chimpanzee R3HCC1 (99% identical), macaque R3HCC1 (96% identical), dog R3HCC1 (77% identical), guinea pig R3HCC1 (74% identical), mouse R3hcc1 (71% identical), rat R3hcc1 (70% identical), zebrafish r3hcc1 (28% identical), Drosophila melanogaster CG2162 (28% identical), Caenorhabditis elegans F09C8.2 (19% identical). Paralogues in human: R3HCC1L (24% identical).
Diseases named in the same sentence as R3HCC1 in open-access papers:
R3HCC1 is named in the same sentence as 4 diseases in open-access papers, as found by Europe PMC text mining. Sharing a sentence is not in itself a finding about the gene and the disease. The quoted sentences say what the papers report.
neutropenia (1 paper, 2023). A decrease in the number of neutrophils found in the blood. "Therefore, the relationship between R3HCC1 gene polymorphism and neutropenia needs to be further validated using a larger sample." (PMID 36308049, 2023). "In conclusion, we suggest that R3HCC1 gene polymorphism (c.919G > A, rs2272761) may be a useful predictive biomarker for severe neutropenia associated with irinotecan‐containing chemotherapy in patients with colorectal and pancreatic cancer." (PMID 36308049, 2023). "Our results showed that an SNP in R3HCC1 (c.919G > A, rs2272761) was useful as a biomarker of hematotoxicity, such as severe neutropenia, in patients who received irinotecan‐containing doublet chemotherapy (i.e., FOLFIRI) for mCRC." (PMID 36308049, 2023).
pancreatic cancer (1 paper, 2023). "Thus, an SNP in the R3HCC1 gene may be a useful biomarker for the toxicity of irinotecan‐containing chemotherapy for mCRC and pancreatic cancer." (PMID 36308049, 2023).
infection (1 paper, 2022). The state of being infected such as from the introduction of a foreign agent such as serum, vaccine, antigenic substance or organism. "After an in vitro infection with Salmonella, R3HCC1 was downregulated in porcine neutrophils." (PMID 37354463, 2022).
R3HCC1 also shares sentences with these, for which no sentence is quoted: entropion (1 paper).